HDAC8 (histone deacetylase 8)
Diseases named in the same sentence as HDAC8 in open-access papers (continued):
Sharing a sentence is not in itself a finding about the gene and the disease.
asthma (5 papers, 2016 to 2023). "Studies revealed that a HDAC8 specific inhibitor (PCI-34051) had advantages in the relief of airway inflammation associated with asthma." (PMID 27565183, 2016). "PCI-34051 was reported to alleviate airway inflammation in a preclinical model of asthma by disrupting HDAC8 interaction with Galectin-3, a protein involved in inflammation and pathogenesis of asthma." (PMID 33922725, 2021). "PCI-34051 alleviated airway inflammation and disrupted HDAC8 interaction with Galectin-3, a protein involved in inflammation and pathogenesis of asthma." (PMID 33922725, 2021). "In this context, a recent study demonstrated therapeutic effects of both HDAC6 and HDAC8 inhibitors in a mouse model of asthma." (PMID 30405614, 2018). "Some inhibitors of HDAC8 that have been recently reported have shown a marked anti-inflammatory potential in some preclinical models of inflammatory and autoimmune diseases such as sepsis, neuro-inflammation, and asthma." (PMID 33922725, 2021). "Though HDAC8 and Gal-3 have been reported as factors involved in pathological process of allergic asthma, a combined pattern of HDAC8 interacting with Gal-3 is still unclear in asthma." (PMID 32111211, 2020). "Additionally, an increase in the enzyme activity is linked to a number of lung diseases such as asthma and COPD, HDAC8 inhibitors are applied for treatment of asthma through decreasing infiltration of inflammatory cells and content of cytokines in lungs." (PMID 32111211, 2020). "Thus, we speculate that a HDAC8 specific inhibitor may relieve airway inflammation, airway remodeling, and airway hypersensitivity via its anti-inflammatory effect; it may also inhibit the persistent inflammation in the airway to relieve the airway remodeling associated with asthma." (PMID 27565183, 2016). "During our previous experiments, we proved that application of PCI-34051, an inhibitor of HDAC8, could relieve the airway inflammation in asthma and the outcome was as effective as the steroid." (PMID 27565183, 2016). "Future studies will employ an early acute asthma model to confirm the hypothesis that specific HDAC8 inhibitors may exert anti-inflammatory effects and the anti-inflammatory, anti-remodeling and anti-hypersensitivity effects are closely related to potent anti-inflammatory activity in asthma." (PMID 27565183, 2016). "However, HDAC8-related macrophage polarization in asthma is still largely unknown." (PMID 32111211, 2020). "Therefore, application of HDAC8-specific inhibitors may represent a mode of treatment for asthma." (PMID 27565183, 2016). "In asthma patients, the interaction between HDAC8 / Gal3 increases the CD163 expression; therefore, given the role of CD163 in M2 differentiation, and the role of M2 cells in Th2 differentiation, CD163 in asthma can be considered as a target for the targeted therapy route." (PMID 37422662, 2023).
glioblastoma (5 papers, 2019 to 2024). The most malignant astrocytic tumor (WHO grade IV). "TMZ treatment causes the dissociation of HDAC8 from ADRM1 in TMZ-sensitive U87 glioblastoma cells." (PMID 31798765, 2019). "Although histone deacetylase 8 (HDAC8) plays a role in glioblastoma multiforme (GBM), whether its inhibition facilitates the treatment of temozolomide (TMZ)-resistant GBM (GBM-R) remains unclear." (PMID 34072831, 2021).
Hypertension (5 papers, 2019 to 2025). The presence of chronic increased pressure in the systemic arterial system. "We and another group showed that HDAC8 is implicated in vascular contractility in hypertension." (PMID 33959033, 2021). "Specific inhibition of HDAC8 can reduce hypertension by inhibiting arterial remodelling, vasoconstriction and inflammation, suggesting that HDAC8 is a regulator of hypertension and a potential therapeutic target." (PMID 40497340, 2025). "We demonstrated that an HDAC8-selective inhibitor lowered blood pressure, inhibited vascular hypertrophy and inflammation, and relaxed blood vessels in an Ang II-induced hypertension model." (PMID 31223486, 2019). "The purpose of this study was to investigate whether PCI34051, an HDAC8-selective inhibitor, can modulate angiotensin II-induced hypertension and its regulatory mechanism." (PMID 31223486, 2019). "In the present study, we demonstrated that PCI34051, an HDAC8-selective inhibitor, lowered systolic blood pressure, reduced aortic wall thickness, increased vascular relaxation, and inhibited inflammation in a mouse model of Ang II-induced hypertension." (PMID 31223486, 2019). "We suggest that HDAC8 may be a therapeutic target for hypertension." (PMID 31223486, 2019). "We suggest that HDAC8 could be a potential therapeutic target for hypertension." (PMID 31223486, 2019). "Therefore, we hypothesized that HDAC8 may have a role in hypertension." (PMID 31223486, 2019). "In our previous studies, we demonstrated that the selective HDAC8 inhibitor, PCI34051, improved vascular hypertrophy in angiotensin II-induced hypertension and the enzymatic activity of HDAC8 was increased in the hearts with deoxycorticosterone acetate-salt induced hypertension." (PMID 33959033, 2021).
Intellectual disability (5 papers, 2021 to 2025). "Wilson–Turner syndrome is a rare X-linked multisystem genetic disease that also manifests with intellectual disability, dysmorphic facial features and short stature and has been linked to a mutation in the HDAC8 gene." (PMID 35454109, 2022). "Multiple missense de novo and pathogenic variants have been reported in HDAC8 in patients with developmental disorders including those with intellectual disability." (PMID 34069769, 2021). "A case report of intellectual disability (ID) showed that neuroligin 4 X-linked (NLGN4X, Gene ID: 57502), histone deacetylase 8 (HDAC8, Gene ID: 55869), TATA-box binding protein associated factor 1 (TAF1, Gene ID: 6872), and USP9X genes were associated with XCI escape." (PMID 39891056, 2025).
myeloproliferative neoplasm (5 papers, 2017 to 2025). A clonal hematopoietic stem cell disorder, characterized by proliferation in the bone marrow of one or more of the myeloid (i.e., granulocytic, erythroid, megakaryocytic, and mast cell) lineages. "Preclinical studies in myeloproliferative neoplasms (MPNs) have evaluated several histone deacetylase inhibitors (HDACs), including panobinostat, vorinostat, givinostat, and PCI34051 (HDAC8-specific)." (PMID 40374809, 2025). "In myeloproliferative neoplasm (MPN) cells, HDAC8 suppresses the expression of SOCS1 and SOC3." (PMID 36231123, 2022).
ovarian carcinoma (5 papers, 2021 to 2026). A malignant neoplasm originating from the surface ovarian epithelium. "PCI‐34051 has been found to inhibit the growth of ovarian cancer and human bronchial smooth muscle cells as an inhibitor of HDAC8." (PMID 41584728, 2026). "Further investigation is required to determine whether inhibition of HDAC6 and HDAC8 has synergistic anti-cancer effects in solid tumors beyond ovarian cancer." (PMID 35955780, 2022). "In this study, we demonstrate, for the first time, the anti-cancer effect of HDAC8 selective inhibitor, PCI-34051, in ovarian cancer." (PMID 35955780, 2022). "However, no study has been conducted on the HDAC8 inhibitor, PCI-34051, in ovarian cancer so far." (PMID 35955780, 2022).
acute lymphoblastic leukemia (3 papers, 2022 to 2025). Leukemia with an acute onset, characterized by the presence of lymphoblasts in the bone marrow and the peripheral blood. "The expression levels of HDAC8 were previously shown to be significantly elevated in various tumors, including urothelial cancer, acute lymphoblastic leukemia (ALL), and multiple myeloma (MM)." (PMID 36497084, 2022). "Accordingly, there is intense interest to develop isoform‐selective HDACi's, notably of HDAC1 and HDAC6 (and HDAC8) HDAC1 is overexpressed in a wide range of solid tumors as well as in several leukemias and lymphomas, including acute lymphoblastic leukemia (ALL), CLL and AML." (PMID 40370107, 2025).
allergic asthma (3 papers, 2020 to 2024). A asthma with a basis in a pathological type I hypersensitivity reaction. "Histone deacetylase 8 inhibitor ameliorates airway hyper-responsiveness and allergic airway inflammation in mice with allergic asthma through declining M2 macrophage polarization." (PMID 38650035, 2024). "The HDAC8 inhibitor attenuates AHR and airway inflammation in the animal model of allergic asthma through suppressing HDAC8-Gal-3 interaction and reducing M2 macrophage polarization." (PMID 32111211, 2020). "The HDAC8 inhibitor ameliorates AHR and airway inflammation in animal model of allergic asthma through reducing HDAC8-Gal-3 interaction and M2 macrophage polarization." (PMID 32111211, 2020).
colitis (3 papers, 2019 to 2022). Inflammation of the colon. "Interestingly, two novel studies have shown that butyrate is able to ameliorate rheumatoid arthritis and colitis by targeting HDAC8 and HDAC1 in Th17 cells, respectively." (PMID 30770822, 2019). "In this study, we hypothesized that the novel HDAC8 inhibitors, SPA3052 and SPA3074, might be possible therapeutics for IBD and evaluated their efficacy and underlying mechanisms of action using a DSS-induced colitis murine model." (PMID 36558966, 2022). "This study aimed to evaluate the efficacy of two novel histone deacetylase 8 (HDAC8) inhibitors, namely, SPA3052 and SPA3074, against dextran sulfate sodium (DSS)-induced experimental colitis." (PMID 36558966, 2022). "In this study, we determined the efficacy of two HDAC8 inhibitor candidates, namely, SPA3052 and SPA3074, against intestinal inflammation in a murine model of colitis." (PMID 36558966, 2022). "Specifically, butyrate downregulates hexokinase-2 (HK2), which is upregulated in inflammation, via histone deacetylase 8 (HDAC8), thus alleviating colitis." (PMID 35050167, 2022). "In summary, this study shows that the novel HDAC8 inhibitor SPA3074 improved the histological score and maintained the tight junction protein levels, thereby strengthening the epithelial barrier in a murine model of colitis." (PMID 36558966, 2022).
heart failure (3 papers, 2022 to 2026). Inability of the heart to pump blood at an adequate rate to meet tissue metabolic requirements. "Here, the effect and regulatory mechanisms of the Hdac8 selective inhibitor PCI34051 on pressure overload-induced heart failure were examined." (PMID 35126818, 2022). "Among class I HDACs, only Hdac8 was upregulated in the cardiac and pulmonary tissues of the heart failure mouse model." (PMID 35126818, 2022). "Treatment with PCI34051 mitigated the TAC-induced changes in the expression levels of these genes, which suggested that HDAC8 promoted the activation of RAAS during heart failure." (PMID 35126818, 2022). "This suggested a distinct role of HDAC8 in the regulation of heart failure." (PMID 35126818, 2022). "This is the first study to demonstrate the role of HDAC8 in the pathogenesis of heart failure." (PMID 35126818, 2022). "We hypothesized that heart failure could also be alleviated through HDAC8 inhibition." (PMID 35126818, 2022). "Thus, HDAC8 is a potential novel therapeutic target for heart failure." (PMID 35126818, 2022). "However, the role of HDAC8 in heart failure has not been elucidated." (PMID 35126818, 2022).
lung disease (3 papers, 2020 to 2022). "HDAC8 participates in the pathogenesis of diseases such as CdLS, infectious disease, cardiovascular disease, pulmonary disease, gastrointestinal disease, hepatic disease, renal disease, neuronal disease, osteopathy, and myopathy." (PMID 36231123, 2022). "Our results not only provide insight into the localization of independent antigens within the tissue and cells but also suggest that HDAC8 and Gal-3 as convergent targets were co-interfered in the antigen-induced lung disease." (PMID 32111211, 2020). "Recent studies have expanded our knowledge of HDAC8 in non-cancer diseases such as cardiovascular disease, pulmonary disease, and myopathy." (PMID 36231123, 2022).
microcephaly (3 papers, 2015 to 2023). A congenital or acquired developmental disorder in which the circumference of the head is smaller than normal for the person's age and sex. "The deletion of Hdac3 and Hdac8 in CNCCs results in various craniofacial deformities, including cleft palate, microcephaly, and calvarial bone defects." (PMID 35242053, 2022).
parasitic infections (3 papers, 2020 to 2025). "HDAC8, an evolutionarily distinct, X-linked, zinc-dependent class I histone/protein deacetylase, is implicated in developmental disorders, parasitic infections, myopathy, and cancers." (PMID 41379555, 2025). "Among them, HDAC8 performs critical functions in diverse biological events including mitosis, transcription, chromatin remodelling and RNA splicing and is implicated as a therapeutic target in various diseases including X‐linked intellectual disability, parasitic infections and cancer." (PMID 34435400, 2021). "Histone deacetylase 8 (HDAC8), one of the crucial HDACs, plays an important role in occurrence and progression of various diseases, including cancer, hereditary disease, and parasitic infections via different signaling pathways." (PMID 33279948, 2020).
schistosomiasis (3 papers, 2020 to 2025). An infectious disease caused by parasitic trematodes of the genus Schistosoma that colonize human blood vessels and release eggs that can cause granulomatous reactions leading to acute (swimmer's itch or acute schistosomiasis syndrome) or chronic disease. "Its uniform superiority in molecular docking, DFT energies, conformational dynamics, MM/GBSA binding energy, and pIC50 prediction highlights its potential as an HDAC8 inhibitor with selectivity and high potency for the treatment of schistosomiasis." (PMID 41438622, 2025). "Histone deacetylase (HDAC) enzymes, particularly HDAC8, are considered valuable for therapeutic intervention for the treatment of schistosomiasis." (PMID 38416775, 2024). "The present study experimentally demonstrates the potential of triazole‐based small‐molecules as potent and selective S. mansoni HDAC8 inhibitors, which could find an application in the treatment of schistosomiasis after improving the bioavailability." (PMID 31816172, 2020).
autism (2 papers, 2021). Persistent deficits in social interaction and communication and interaction as well as a markedly restricted repertoire of activity and interest as well as repetitive patterns of behavior. "To identify potential epigenetic aberrations in the VPA-induced autism model, we examined the levels of class I HDACs (HDAC1, HDAC2, HDAC3, and HDAC8) and AcH3 in the PFC nuclear fraction." (PMID 33994921, 2021).
breast tumor (2 papers, 2015 to 2017). "For example, in breast tumor MCF7 cells and neuronal fibroblasts, inhibition or defects in HDAC8 prolongs G1 phase and delays entering to S phase." (PMID 28509866, 2017).
diabetes (2 papers, 2016 to 2020). "In contrast, the potential of HDAC8 inhibitors for diabetes treatment has not yet been reported." (PMID 27247940, 2016).
diaphragmatic hernia (2 papers, 2019 to 2024). A congenital or acquired weakness or opening in the diaphragm which allows abdominal contents to protrude into the chest cavity; congenital diaphragmatic hernias are caused when the embryonic diaphragm fails to fuse. "The child had renal anomalies and a diaphragmatic hernia, consistent with known HDAC8-associated clinical variations." (PMID 38673696, 2024).
Duchenne muscular dystrophy (2 papers, 2022 to 2023). Duchenne muscular dystrophy (DMD) is a neuromuscular disease characterized by rapidly progressive muscle weakness and wasting due to degeneration of skeletal, smooth and cardiac muscle. "Clinical studies have shown that HDAC8 is overactivated in skeletal muscle of patients with Duchenne Muscular Dystrophy (DMD)." (PMID 38148899, 2023). "HDAC8 mediates various myopathies, such as Duchenne muscular dystrophy (DMD), rheumatoid arthritis (RA), and osteoarthritis (OA)." (PMID 36231123, 2022).
idiopathic pulmonary arterial hypertension (2 papers, 2020 to 2022). A sporadic form of pulmonary arterial hypertension (PAH) characterized by elevated pulmonary arterial resistance leading to right heart failure. "One study reported that the expression levels of HDAC1, HDAC2, and HDAC8 were upregulated in patients with idiopathic pulmonary arterial hypertension." (PMID 35126818, 2022). "Comprehensive analysis of expression and regulation of class I HDACs (HDAC1, HDAC2, HDAC3 and HDAC8) was performed in cardiopulmonary tissues and adventitial fibroblasts isolated from pulmonary arteries (PAAF) of idiopathic pulmonary arterial hypertension (IPAH) patients and healthy donors." (PMID 32733053, 2020).
lymph node metastasis (2 papers, 2016 to 2023). "In addition, the expression of HDACs 2 and 3 proteins, but not HDAC8, was positively correlated with lymph node metastasis, TNM stage, and differentiation." (PMID 27705912, 2016).
malignant peripheral nerve sheath tumor (2 papers, 2015 to 2023). Malignant peripheral nerve sheath tumor (MPNST) is a rare and often aggressive soft tissue sarcoma occurring in a wide range of anatomical sites. "Modulation of cell cycle has been reported with selective HDAC8 inhibition in malignant peripheral nerve sheath tumors, while others claim that HDAC8 inhibition leads to enhanced immune infiltration." (PMID 36595522, 2023). "HDAC8 inhibitors are novel compounds and have affinity for class I HDAC isoforms demonstrating anti-cancer effects; little is known about their activity in malignant peripheral nerve sheath tumors (MPNST)." (PMID 26200462, 2015).
mantle cell lymphoma (2 papers, 2022). Mantle cell lymphoma is a rare form of malignant non-Hodgkin lymphoma affecting B lymphocytes in the lymph nodes in a region called the ``mantle zone''. "The potential involvement of HDAC8 was also explored in mantle cell lymphoma (MCL), a severe non-Hodgkin lymphoma that requires the use of high-dosed antitumour drugs with a negative impact on the therapeutic index." (PMID 36077415, 2022). "In mantle cell lymphoma (MCL), HDAC8 inhibition has been observed to increase interferon-gamma (IFNγ)-producing NK cells." (PMID 36231123, 2022).
oral cancer (2 papers, 2019 to 2023). "It is found that knockdown of HDAC8 promotes autophagy which relates to the inhibition of growth in oral cancer cells." (PMID 31817161, 2019). "Inhibition of HDAC8 by the deacetylase inhibitor apicidin was further shown to induce cell growth inhibition and enable apoptosis as well as autophagy in murine OSCC and in MEC, indicating HDAC8 inhibition as a new agent in oral cancer." (PMID 37887281, 2023).